ENO1 (enolase 1)
Diseases named in the same sentence as ENO1 in open-access papers (continued):
Sharing a sentence is not in itself a finding about the gene and the disease.
tumor (continued). "Experimental evidence suggests that circUBE2G1-99aa inhibits GC cell proliferation, potentially through binding to the ENO1 enzyme and modulating the ENO1/PI3K/AKT pathway, thereby suppressing glycolysis and altering tumor metabolism." (PMID 40730815, 2025). "It is worth mentioning that several reports have shown elevated levels of these gluconeogenesis-related genes, especially ENO1, PGK1, and PKM, in tumor tissues." (PMID 40821334, 2025). "Functional assays with the TLR4 inhibitor TAK-242 demonstrated that TLR4 blockade reversed rhENO1-induced tumor proliferation, migration, and invasion, confirming TLR4’s role in ENO1-driven malignancy." (PMID 41353343, 2025). "IHC analysis of human GBM specimens revealed a positive correlation between ENO1 expression and CD163+ M2-TAM infiltration in tumor stroma." (PMID 41353343, 2025). "In NSCLC, ENO1 promotes cell proliferation through the focal adhesion kinase (FAK)-mediated PI3K/AKT pathway, further contributing to tumour progression." (PMID 41154605, 2025). "On the other hand, we found an enrichment of hypoxia related terms for NMF_4 and NMF_5 with the top genes VEGFA, NDRG1, and ENO1, markers of previously reported “MES-hypoxia” tumor cell state." (PMID 40781324, 2025). "As a control, we analyzed the mammary fat pad of non-tumor-bearing mice, which showed the low expression of PADI2 and citENO1 and the moderate expression of ENO1." (PMID 40573960, 2025). "According to the TMA, the CD41-high expression group had significantly greater expression levels of LINC00183, ENO1, H3K18la, and GDF15 in CRC tumor tissues than the CD41-low expression group." (PMID 40775002, 2025). "Subcutaneous injection was used to generate mouse xenograft tumor models of MIA Paca-2 cells overexpressing PGM2L1, ENO1, co-expressing, and the control into the right dorsolateral regions of these nude mice (n = 4 per group)." (PMID 40507914, 2025). "Enolase 1 (ENO1), another key glycolytic enzyme in GC, directly interacts with PKM2, facilitating aerobic glycolysis, tumor cell proliferation, migration, and apoptosis resistance." (PMID 41169372, 2025). "In our study, nuclear PKM2 acted as a protein kinase, promoting the phosphorylation of STAT3, thereby regulating the expression of downstream glycolysis-related genes such as GLUT1, ENO1, and LDHA, which in turn promotes tumor progression." (PMID 39368995, 2024). "In mice bearing HCC, PP injection inhibited the overexpression of ENO1, affected serum ALT, AST, and AST/ALT levels, and reduced tumor weight." (PMID 39576845, 2024). "This metabolism enrichment highlighted enzymes at the interface between glycolysis (GAPDH, ENO1, LDHA) and one-carbon metabolism (TYMS, SHMT2, MTHFR, MTHFD1), further confirming the importance of these two pathways in CIMP tumours." (PMID 38540202, 2024). "EV-derived ENO1 can upregulate integrin α6β4 expression and activate the focal adhesion kinase (FAK)/Src/p38 pathway to promote tumor growth and metastasis of HCC cells." (PMID 39227992, 2024). "By combining with glycolytic enzymes such as ENO1 and PKM2 to form multi‐enzyme complexes, Hsp90 improved glycolytic efficiency, thereby promoting tumor proliferation and stemness." (PMID 38874476, 2024). "We have demonstrated that PI3Kγ inhibition combined with the ENO1 DNA vaccine reduces tumor growth, increases immune infiltration at tumor sites, modulates the TME and strongly potentiates the ENO1-specific humoral and cellular responses." (PMID 38824552, 2024).
tumor (continued). "In summary, our findings highlight that USP21-mediated post-translational regulation of HSP90 and ENO1 is important in aerobic glycolysis and CCA tumor progression and provide an option for cancer therapy targeting glucose metabolism." (PMID 38385089, 2024). "Hypoxia has been found to enhance lactate production and tumor growth through activation of HIF1-α, GLUT1, HK2, PKM2, PDK, ENO1 or LDHA." (PMID 38233839, 2024). "Emerging studies have shown the upregulation of enzymes hexokinase-2 (HK2), phosphofructokinase, enolase 1 (ENO1), and pyruvate kinase M2 (PKM2) in animal models and human cells stimulated with tumor extract solution." (PMID 37426676, 2023). "Mechanistically, targeted depletion of ENO1 and FDPS halted TNBC cell proliferation, colony formation, and organoid tumor growth under 3-dimensional conditions and increased cell death, suggesting their potential use as novel therapeutic targets for TNBC." (PMID 37190091, 2023). "Alternatively, the selection of potent tumor-suppressing proteins such as CALR, ENO1, PCOLCE, etc. can be another option to construct a protein cocktail." (PMID 36943734, 2023). "Considering the head body of the pancreas as the tumor site, a slight relationship of both FUBP1 and ENO1 aAb titer with the prognosis was observed." (PMID 37910256, 2023). "As an alternative option, the combination of multiple tumor-suppressing proteins such as PABPC1, ENO1, MSN, etc. can be considered a protein-based cocktail therapy." (PMID 36923539, 2023). "This study revealed the unconventional use of tumorigenic factors such as PABPC1, ENO1, and MSN as extracellular tumor-suppressing proteins, which were enriched in AMPK-inhibited PBMC/lymphocyte-derived CM." (PMID 36923539, 2023). "The results indicated that ENO1, MSN, and PABPC1 were double-edged swords, acting as intracellular tumor promoters and extracellular tumor suppressors." (PMID 36923539, 2023). "Based on matched tumor and normal tissues from the patients in Human Protein Atlas, we found both PGAM1 and ENO1 were up-regulation in tumor side." (PMID 37065499, 2023). "In the TCGA database, five transcripts for the selected tumor-suppressing proteins (CALR, ENO1, HSP, MSN, and UBC) were significantly upregulated in OS cells." (PMID 36943734, 2023). "In addition, we checked whether KIAA1429 and ENO1 were correlated in other tumor tissues." (PMID 37807062, 2023). "Mass spectrometry-based proteomics together with a reciprocal immunoprecipitation predicted the interaction of Mtdh with MSN and ENO1, and RNA interference with Mtdh siRNA supported Mtdh-mediated anti-tumor actions of MSN and ENO1." (PMID 36923539, 2023). "The results indicated that melatonin treatment or silencing of ENO1 significantly inhibited tumor growth compared with the PBS-treated group, and combined use further reduced the tumor size." (PMID 37024456, 2023). "The tumor-suppressing actions of MSN and ENO1 were at least in part mediated by Metadherin (Mtdh), which is known to promote metastatic seeding." (PMID 36923539, 2023). "Our previous findings on the role of ENO1 in tumorigenesis and tumor metabolism enabled the correlation analysis between TYRO3 and ENO1 expression." (PMID 37116196, 2023). "Previous studies for iTSCs showed that MSC CM, generated by the activation of Wnt and PI3K signaling pathways, were enriched with extracellular tumor-suppressing proteins such as CALR, ENO1, HSP, MSN, and UBC." (PMID 36943734, 2023). "In-depth analysis of the tumor revealed that UPP1 Knockdown induced apoptosis and decreased the expression of ENO1 and LDHA." (PMID 36186123, 2022). "The individual and combined efficacies of Hsp90ab1 and Eno1 recombinant proteins were plotted in the concentration range of 1 ng/mL to 5 μg/mL, showing their additive anti-tumor effects on MTT-based tumor viability." (PMID 35547745, 2022). "It targeted ALDO, LDHA, ENO1, PGK1, CA9, and other genes in the invasive tumor and the hypoxic tumor." (PMID 36685583, 2022).
tumor (continued). "Overexpression of enolase 1 (ENO1), another glycolytic enzyme, in HCC, especially in metastatic lesions, can often indicate worse clinical characterizations including tumor-node-metastasis (TNM) stage, differentiation grade, and poorer prognosis." (PMID 35924040, 2022). "The expression levels of key glycolytic enzymes, namely GLUT1, ENO1, PGK1, ALDOA, HK1, and LDHA, in the tumor tissues of chemotherapy-resistant and chemotherapy-sensitive groups were examined using IHC analysis." (PMID 34510316, 2022). "Specifically, CD44 was co-immunoprecipitated with Eno1 and the silencing of CD44 suppressed Eno1's anti-tumor action." (PMID 35547745, 2022). "Among the proteins with higher prot_score, ENO1, TUBB3, MYH9 and YBX1 were reported to promote or inhabit tumor progression by interacting with lncRNAs 46-51." (PMID 35541917, 2022). "Next, we examined the expression of key enzymes catalysing glycolysis such as PFKP, ENO1, PKM and LDHA in ccRCC tumours and the matched controls." (PMID 35672925, 2022). "Osteoclast secretome-derived Hsp90ab1 and Eno1 inhibited tumor progression by suppressing TGF-ß signaling and interacting with CD44, facilitating tumor cell killing by natural killer (NK) cells." (PMID 35994202, 2022). "The findings also showed that the mRNA expression of CNTN1, ENO1, and MAGEA1 were higher in tumor tissues, whereas the mRNA expression of GATA3 was higher in normal tissues." (PMID 35846128, 2022). "The immunoprecipitation result indicated that extracellular Eno1 interacted with a membrane-bound CD44 in tumor cells and suppressed the progression of tumor cells." (PMID 35547745, 2022). "In consistence with this, the expression of ENO1 and PDK1 were elevated and PRKCB was decreased in matched LUAD tumor tissues compared with normal tissues." (PMID 35504868, 2022). "The results showed that, both in tumor tissues and normal tissues, CCDC65 was negatively correlated with ENO1 or c-Myc expression." (PMID 35844805, 2022). "Western blotting was used to assess the levels of ENO1, c-Myc, β-catenin, MMP-9, PGAM1, and MMP-13 in SKCM-derived cell lines or tumor tissues from patients with SKCM." (PMID 35925486, 2022). "The qRT-PCR results demonstrated that expression of CNTN1, ENO1, and MAGEA1 were higher in tumor tissues, whereas the expression of GATA3 was higher in normal tissues." (PMID 35846128, 2022). "In addition, ENO1 might have an important function in tumor cell glycolysis." (PMID 35925486, 2022). "The serum levels of tumor markers such as CA19-9, CA242, and CEA were positively correlated with ENO1 expression." (PMID 36476328, 2022). "Immunohistochemistry and mRNA detection were performed on the tumor, and the results confirmed that the expression of FAM126A and ENO1 was consistent with the results verified before the tumogenesis experiment in nude mice." (PMID 35513377, 2022). "As a key transcription factor, SIX1 has been implicated in the glucose metabolism that promotes glycolysis and tumor growth by stimulating glycolytic genes (such as GLUT1, ENO1, and LDHA) transcription." (PMID 32399910, 2021). "ENO1 and JMJD6 were moderately positive while SLC2 was weakly positive in HCC tissues when compared with corresponding expression levels in non-tumor tissues." (PMID 34194464, 2021). "By real-time qPCR analysis, we found that CD73 knockdown can lead to significant down-regulation of glycolytic genes (GLUT1, HK2, ENO1, and LDHA) in tumor tissues from the subcutaneous xenograft model." (PMID 34659527, 2021).
tumor (continued). "Moreover, statistical analysis revealed that high ENO1 immunohistochemical expression levels in both ESCC and EAC were significantly associated with disease stage, but not with other clinical features such as age, gender, tumor location, or degree of tumor differentiation." (PMID 33628097, 2021). "In this study, we identified CD44 as a binding partner of Eno1 and observed CD44-mediated inhibition of Eno1's anti-tumor action." (PMID 34373756, 2021). "IHC revealed that the tumor tissue grown from sh-AL355338 cells displayed lower Ki-67, ENO1, and EGFR staining than those formed from sh-NC cells." (PMID 34627260, 2021). "The expression of c-Myc-regulated genes including LDHA, ENO1, and PFK in tumor C4-2B grafts (LKO vs. sh4B#1) was then compared using qRT-PCR analysis." (PMID 34335964, 2021). "ENO1 mRNA levels were higher in both human PDA cell lines and tumor tissue derived from the same cells injected into nude mice, compared to normal pancreata." (PMID 33804240, 2021). "Analysis of TAMs from MMTV-PyMT mice and BMDMs stimulated by tumor extract from MMTV-PyMT mice revealed the significant increase in HK2, enolase 1 (ENO1), and 6-phosphofructokinase (PFKL), a key mediators of aerobic glycolysis." (PMID 32486098, 2020). "Its localization in the tumor surface, key metabolic functions, and ability to promote tumor aggressive properties could be exploited for the development of novel comprehensive cancer care modalities that combine ENO1 surface imaging with targeted therapeutic interventions." (PMID 33584813, 2020). "Because PKM2 is a fundamental enzyme for regulation of aerobic glycolysis in tumor cells, we further determine that PTBP1 expression is positively correlated with aerobic glycolysis genes including LDHA, HK2, and ENO1." (PMID 32655719, 2020). "ENO1 showed correlation with immune infiltrates including B cells, CD8+ and CD4+ T cells, macrophages, neutrophils, and dendritic cells, and tumor purity." (PMID 33643901, 2020). "Among the four selected genes, ENO1, GAPDH, and SLC2A1 were significantly upregulated in tumor tissues compared with normal tissues." (PMID 32084009, 2020). "Based on current reports on integrins in tumor research, especially in the HCC field, we first tested the effect of ENO1 knockdown on the expression of related integrins (α1, α2, α3, α5, α6, αV, β1, β3, β4, and β6) in HCCLM3 cells." (PMID 33184263, 2020). "Enolase 1 (ENO1) is a glycolysis enzyme for glucose metabolism, and contributes to tumor progression." (PMID 33643900, 2020). "Additionally, mutation of ENO1 was analysis, for it was proved that mutation could affect tumor progression; however, ENO1 mutation (1.8%) did not impact on prognosis in this study." (PMID 33643901, 2020). "All non-tumoral breast tissues showed low expression/activity of both ENO1 and MMP-2 and MMP-9, whereas higher expression/activity was observed in the paired tumour samples." (PMID 31416219, 2019). "In summary, current study elucidated that circ-ENO1 promoted glycolysis and tumor progression in LUAD by miR-22-3p/ENO1 axis, indicating circ-ENO1 as a promising treatment target for LUAD patients." (PMID 31767835, 2019). "Recent studies have demonstrated that ENO1 is overexpressed in HCC tissue, which is correlated with the degree of tumor differentiation and progression." (PMID 30518748, 2018). "For each tumor, we dissected 4–5 separate frozen regions and determined the mRNA expression of TMPRSS2, GPI and ENO1 with qRT-PCR." (PMID 30478344, 2018). "The cBio Portal generated a network showing that ENO1, PTGES3, NPM1 and STMN1 are connected in this tumor." (PMID 29545914, 2018). "The results indicated that the ENO1 levels in tissues and peripheral blood of PDAC patients were related to the regional development of the primary tumor." (PMID 29483925, 2018).
tumor (continued). "For in vivo investigations, ENO1-silenced or control CFPAC-1 and MDA-MB-231 cells were subcutaneously (s.c.)injected into the flanks of SCID-beige mice, and tumor growth was monitored." (PMID 26734996, 2016). "Therefore, we wish to develop a nanoparticle formulation modified with tumor-targeting single-chain antibody fragment (scFv) for systemic delivery of siRNA-ENO1 in the future, which may make it possible that ENO1 serves as a molecular therapeutic target for NSCLC treatment." (PMID 25887760, 2015). "In contrast to other human cancers where ENO-1 acts as pro-oncogenic agent, in PDAC ENO-1 favors anti-tumor responses." (PMID 25407528, 2014). "Immunoprecipitation analyses verified the expression and citrullination of ENO1, HSP60, KRT8, and TUBB in the total protein lysates of the tumour cell lines." (PMID 24099319, 2013). "We demonstrated that blocking of surface ENO1, which was confirmed to promote ECM degradation and invasion of cancer cells, by treatment with Ab against ENO1 delays tumor lung and bone metastasis in mice." (PMID 23894455, 2013). "The current study identified novel citrullinated proteins, including ENO1, HSP60, KRT8, and TUBB, in tumour cells." (PMID 24099319, 2013). "Enolase 1 (ENO1) is a glycolytic enzyme involved in tumor progression that performs a variety of classical and nonclassical functions." (PMID 41629269, 2026). "To further investigate ENO1-associated non-glycolytic metabolic pathways in tumor progression, we analyzed proteomic profiles of 110 GBM patients from the Clinical Proteomic Tumor Analysis Consortium (CPTAC) database." (PMID 41353343, 2025). "Although no inhibitors of PGM2L1 have been discovered, inhibitors of ENO1 have shown good tumor suppression effects." (PMID 40507914, 2025). "Interestingly, ENO1 is also related to B cells, CD4+ T cells, and macrophages in the infiltrating tumor tissues (P < 0.001)." (PMID 41049005, 2025). "The univariate analysis revealed that several factors, including the degree of tumor differentiation, vascular and neural invasion, depth of tumor infiltration, lymph node metastasis, as well as the expression levels of ALDOA and ENO1, significantly influenced patient survival (P < 0.05)." (PMID 41049005, 2025). "Thus, the therapeutic efficacy of ENO1 inhibitors, such as POMHEX, requires further validation in immunocompetent mouse models to balance tumor suppression with immune preservation." (PMID 40734168, 2025). "Overall, we concluded that ENO1 synergistically regulated the PI3K/AKT and AMPK/mTOR pathways through direct stimulation of glycolytic products and influenced the ATP pool and lactate homeostasis, ultimately promoting the stemness and tumor growth of GCs." (PMID 41168198, 2025). "When we observed that KPC/IL17A−/− tumours were much more infiltrated by CD8+ T cells and significantly less by Treg, we thought to exploit the TME reshaping mediated by the IL17A's depletion to improve the ENO1‐DNA vaccine efficacy." (PMID 40831074, 2025). "Furthermore, Mice injected with WT and ENO1-KO cells were treated with SPP1 inhibitor, revealing that ENO1 knockdown combined with SPP1 inhibitor treatment significantly inhibited tumor growth." (PMID 40665335, 2025). "In cancers, ENO1 has a non-metabolic function as a plasminogen receptor in the tumour cell surface, enhancing proliferation, migration, invasion, and metastasis." (PMID 41154605, 2025). "Regarding ENO1, future studies with larger sample sizes are essential to elucidate its interaction with ZEB1 and its subcellular localization in tumor cells, as these factors provide significant information on tumor progression and prognosis." (PMID 40005870, 2025). "The mRNAs levels of HPD, TPI, and ENO1 were not significantly different between tumor tissues and normal ovarian tissues." (PMID 40491422, 2025).